MED23 (mediator complex subunit 23)
Diseases named in the same sentence as MED23 in open-access papers (continued):
Sharing a sentence is not in itself a finding about the gene and the disease.
lung adenocarcinoma (2 papers, 2024 to 2025). A carcinoma that arises from the lung and is characterized by the presence of malignant glandular epithelial cells. "To further characterize the lung adenocarcinomas in Med23‐deficient mice, we performed whole exome sequencing and found that Med23−/− lung adenocarcinomas displayed increased single nucleotide polymorphism (SNP) mutation rate compared with those of Med23−/− normal tissue controls." (PMID 40344646, 2025). "To determine whether Med23−/− T cells impact mutation accumulation before lung adenocarcinoma initiation, we examined the mutation rate of normal lung tissues in WT and Med23−/− aged mice." (PMID 40344646, 2025). "Indeed, we found that approximately 2.1% of lung adenocarcinoma patient samples in the TCGA database had mutations in MED23 utilizing relevant website analysis, and most of the mutations in MED23 led to a reduction in the copy number of MED23." (PMID 38195889, 2024). "Altogether, these data proved that certain AT2 cells with excessive oxidative stress give rise to lung adenocarcinoma in Med23−/− mice." (PMID 40344646, 2025). "In a mouse model with Med23 depletion in T cells (Med23−/−), it is found a strong association between the decline of CD103+ T cells and spontaneous alveolar epithelial type II cell (AT2 cell)‐originated lung adenocarcinomas." (PMID 40344646, 2025). "Furthermore, we reanalyzed a cDNA array derived from 24 lung adenocarcinoma patient samples reported in our previous study to determine the mRNA levels of MED23 in tumor and adjacent tissues." (PMID 38195889, 2024). "To further confirm the role of CD103+ T cells during lung adenocarcinoma initiation, we adoptively transferred purified CD103− T cells or CD103+ T cells into WT‐KRAS (G12D) and Med23−/−‐KRAS (G12D) mice and induced the KRAS (G12D) expression after that." (PMID 40344646, 2025). "Interestingly, Med23−/− mice spontaneously develop tumors within multiple organs, with alveolar epithelial type II cell (AT2 cell)‐originated lung adenocarcinoma as a major manifestation." (PMID 40344646, 2025).
atherosclerosis (1 paper, 2022). A disease characterized by the build-up of fatty material and calcium deposition in the arterial wall resulting in partial or complete occlusion of the arterial lumen. "Thus, an association has been established between several stretch-specific miR-1183 targets and cardiac remodeling, such as: KCNA3 with diabetic cardiomyopathy, MED23 with CHD, SAMSN1 with atherosclerosis, CCND1 with myocardial ischemia-reperfusion injury, and MCOLN3 with atrial fibrillation." (PMID 35805966, 2022).
autosomal recessive intellectual disability (1 paper, 2020). "Missense mutations in Med23 have been reported in families with autosomal recessive intellectual disability." (PMID 32850819, 2020).
bile duct carcinoma (1 paper, 2025). "Similarly, in humans, Mediator subunits MED12, MED14, MED23, and MED24 interact with YAP in bile duct carcinoma cells." (PMID 39752503, 2025).
cognitive decline (1 paper, 2025). "Utilizing gene-editing technologies, researchers have developed a Med23 mutant mouse model, which demonstrates that Med23 mutations lead to characteristic hypomyelination phenotypes, including cerebral white matter atrophy and cognitive decline." (PMID 40761314, 2025).
Cognitive impairment (1 paper, 2025). Abnormal cognition is characterized by deficits in thinking, reasoning, or remembering. "Animal studies have shown that mice with Med23 mutations exhibit hypomyelination and cognitive impairments; however, the functional restoration of MED23 through gene editing has been observed to restore oligodendrocyte maturation and myelin regeneration." (PMID 40761314, 2025).
demyelinating disease (1 paper, 2024). A broad group of disorders that affect the myelin sheaths that cover the neurons. "In summary, we identified Mediator Med23 as a previously unknown regulator in myelin development and revealed novel molecular mechanisms for OL cell fate determination, providing potential therapeutic targets for demyelinating diseases." (PMID 39402028, 2024).
esophageal squamous cell carcinoma (1 paper, 2022). Esophageal squamous cell carcinoma (ESCC) is a type of esophageal carcinoma (EC) that can affect any part of the esophagus, but is usually located in the upper or middle third. "Conversely, overexpression of MED23 in esophageal squamous cell carcinoma dramatically inhibited cell growth." (PMID 35672824, 2022).
intellectual disability syndrome (1 paper, 2025). "Common to these sets of m6A and m5C effector proteins were the proteins MED23 and MED25 which cause AR ID, syndromic ID and eye–intellectual disability syndrome and which are components of the mediator complex which repress transcription by RNA polymerase II." (PMID 39499421, 2025).
intracranial hemorrhage (1 paper, 2022). Bleeding within the SKULL, including hemorrhages in the brain and the three membranes of MENINGES. "The mutant embryos exhibited intracranial hemorrhage and diminished angiogenesis with dilated blood vessels in the head region, where the expression of Med23 was abundant at E10.5." (PMID 35440711, 2022). "Nearly 70% of Med23-mutant embryos showed intracranial hemorrhage and edema starting from E10.5." (PMID 35440711, 2022).
leukemia (1 paper, 2018). A malignant (clonal) hematologic disorder, involving hematopoietic stem cells and characterized by the presence of primitive or atypical myeloid or lymphoid cells in the bone marrow and the blood. "Further investigations should be conducted to elucidate the underlying mechanisms and to determine whether Med23 can serve as a potential target for defining new approaches to leukemia therapy." (PMID 30218073, 2018). "If so, targeting Med23 in LSCs or leukemia blasts may trigger the differentiation program and leads to the exhaustion of LSCs and leukemia blasts." (PMID 30218073, 2018). "Here, in this study, we show that Med23 deletion leads to impaired HSC self-renewal accompanied with enhanced myeloid differentiation, highlighting the possibility that Med23 may serve similar function in leukemic stem cells (LSCs) and leukemia blast." (PMID 30218073, 2018).
liver disease (1 paper, 2019). "In the future, it will be interesting to define the dynamic interacting protein network with which Mediator MED23 participates in the different diseases and to determine exact molecular mechanisms underlying the liver disease–related transcription regulation." (PMID 31805036, 2019).
Obesity (1 paper, 2023). Accumulation of substantial excess body fat. "Similarly, Med23 LKO were also refractory to high-fat-diet-induced obesity, showing improved glucose and lipid metabolism due to gluconeogenesis deceleration, which is directly modulated by FOXO1, whose interaction with its response elements is disrupted by Med23 deletion." (PMID 37298278, 2023).
prion disease (1 paper, 2024). A transmissible disease that is caused by a protein that is able to induce abnormal folding of normal cellular proteins, leading to characteristic spongiform brain changes, which are associated with neuronal loss without an inflammatory response. "The orthologs of MED23 and Spn42De in humans are responsible for intellectual developmental disorder 18 and prion disease, respectively." (PMID 39337379, 2024).
steatosis (1 paper, 2019). Increased lipid within the cytoplasm of cells. "We also examined the effect of hepatic Med23 deficiency in another NASH model, which used a methionine and choline-deficient (MCD) diet to induce liver pathology including steatosis, liver inflammation and fibrosis, and hepatocyte death (Wang and colleagues, 2016)." (PMID 31805036, 2019).
cancer (10 papers, 2014 to 2025). A tumor composed of atypical neoplastic, often pleomorphic cells that invade other tissues. "Evidence suggests that Mediator complex subunit 23 (Med23) regulates diverse biological processes, including developmental abnormalities, metabolic disorders, and cancers." (PMID 40705824, 2025). "The Med23 subunit is considered a component of the Mediator complex that relays Ras/MAPK signaling to regulate cell fate decisions, cell proliferation, and cancer initiation." (PMID 35440711, 2022).
tumor (7 papers, 2015 to 2025). "Mice with lung-specific Med23 deficiency also exhibited accelerated tumourigenesis, and a higher proliferation rate for tumour cells, along with increased ERK phosphorylation." (PMID 38195889, 2024). "By affecting tumor progression and proliferation, Med23 deficiency in KrasG12D mice resulted in an increasing number of tumors in the lungs." (PMID 38195889, 2024). "The identified somatic variants in the transcriptional activators ZNF225 and MED23 seem to be associated with the deregulation of gene expression and play a role in tumor pathogenesis and potential progression (particularly MED23)." (PMID 38721148, 2024). "To explore the cellular mechanisms by which Med23 deficiency promotes lung tumorigenesis, we analyzed several biological processes associated with tumor formation." (PMID 38195889, 2024). "Overall, these results suggested that Med23 deficiency may alter the immune cell recruitment to the tumor microenvironment, enabling the Med23-deficient tumors to escape immune surveillance and elimination." (PMID 38195889, 2024). "Here, we found that loss of Med23 affected the infiltration of immune cells and the tumor microenvironment, which implied immunotherapy might have better efficacy in patients with low MED23 expression." (PMID 38195889, 2024). "In summary, this study reveals that deficiency in the Mediator component MED23 may aggravate Kras-induced lung tumorigenesis in vivo by reprogramming the tumor microenvironment." (PMID 38195889, 2024). "To understand this paradox, we hypothesized that the tumor microenvironment may contribute to the difference between the in vitro and in vivo phenotypes of Med23 deficiency." (PMID 38195889, 2024). "Moreover, Med23 deficiency in iNKT cells resulted in attenuated anti-tumor activity after α-GalCer administration." (PMID 30250136, 2018). "Together, these data suggest that Med23 deficiency can impair the anti-tumor effects of iNKT cells." (PMID 30250136, 2018). "In particular, the anti-tumor activity of Med23-deficient iNKT cells is significantly attenuated." (PMID 30250136, 2018). "Moreover, Med23-deficient iNKT cells exhibit impaired anti-tumor activity." (PMID 30250136, 2018). "Since the lung appeared to be one of the major organs bearing tumors in the Med23−/− mice, we next focused on the lung to unravel the relationship between T cell dysfunction, tissue fitness and tumor initiation." (PMID 40344646, 2025). "As there were huge changes in tumor number and size after Med23 deletion, we sought to analyze the impact of Med23 on the histological classification of tumors by staining." (PMID 38195889, 2024). "We observed that lung epithelial Med23 deletion by adeno-Cre resulted in a significant increase in KrasG12D tumour number and size, which was further verified with another mouse model with Med23 specifically deleted in alveolar type II cells." (PMID 38195889, 2024). "Overall, Med23 deletion appears to enhance the Kras-driven tumorigenesis via effects on tumor progression and cell proliferation." (PMID 38195889, 2024). "A similar tendency of tumor development was observed in both male and female Med23−/− mice." (PMID 40344646, 2025). "However, it is technically challenging for us to investigate the stimulation of CD4+ and CD8+ T cells in vivo and its direct effect on tumor burden in Med23 knockout mice and the detailed mechanism needs to be further studied." (PMID 38195889, 2024). "However, at 16 weeks post-Adeno Cre infection, KrasG12D/+;Med23f/f mice showed dramatically more and larger tumor nodules on the lung surface than KrasG12D/+;Med23+/+ mice." (PMID 38195889, 2024). "Therefore, the role of Med23 in the tumor-directed immune response is complex and might be context dependent." (PMID 38195889, 2024).
tumor (continued). "Since Med23 deletion exerts opposite effects on lung tumorigenesis in vitro and in vivo, we speculated that host factors, such as the tumor microenvironment, may contribute to the apparent discrepancy between the in vitro and in vivo phenotypes of Med23 deletion." (PMID 38195889, 2024). "Without α-GalCer injections, Med23−/− mice exhibited better anti-tumor effects than did WT controls, probably due to the hyperactivation of T cells." (PMID 30250136, 2018). "Several of the remaining 21 genes not in the GS, such as MYH14, MED23, and ZFP36L1 in BRCA, and ZNF292, FUBP1, and DTX1 in CLL, had also been implicated in tumor development." (PMID 29030609, 2017). "Moreover, the reduction of CD103+ T cells in the lung, the liver and the small intestine is accompanied by spontaneous epithelial cell‐derived tumors in these tissues of Med23−/− mice, implying the importance of CD103+ T cells in surveilling epithelial cell‐derived tumor." (PMID 40344646, 2025). "Interestingly, when reanalyzed the cDNA array data we previously published, we found that not all the patients had high MED23 expression in their tumor tissues and that a few patients (4/24) showed lower MED23 expression in their tumor tissues than in adjacent tissue." (PMID 38195889, 2024). "We thus propose the following model: MED23 may control immunogenicity, as MED23 deletion causes low levels of the MHC-I complex accompanied by low levels of CD8+ T lymphocytes, cytokines, chemokines and PD1, which formed a noninflamed (or cold) tumor microenvironment to promote tumorigenesis." (PMID 38195889, 2024).
neurological diseases (2 papers, 2024 to 2025). "Overall, our findings provide insight into the mechanistic underpinnings of the MED23-associated neurological disorders and enlighten the possible therapeutic interference strategies." (PMID 39402028, 2024). "In our study, the functional importance of the Mediator Med23 in myelin development and related neurological diseases was revealed by utilizing the cellular differentiation system and lineage-specific Med23 inactivation mouse model." (PMID 39402028, 2024).
adenocarcinoma (1 paper, 2025). A common cancer characterized by the presence of malignant glandular cells. "Using a mouse model with Med23 deletion in T cells, we uncover a strong association between the decline of CD103+ T cells and the tumorigenesis of AT2‐originated adenocarcinoma in the lung." (PMID 40344646, 2025). "In this study, we found Med23 deletion in T cell compartment reduces CD103+ T cells, which give rise to an accumulation of oxidative stressed AT2 epithelial cells which appear to be a key origin of adenocarcinoma during aging." (PMID 40344646, 2025).
brain diseases (1 paper, 2025). "Collectively, our data demonstrate Med23 deficiency causes DG malformation and ADHD-like behaviors, suggesting a novel mechanism underlying relevant brain diseases." (PMID 40114018, 2025). "Considering the similar phenotypes of ADHD patients and the usefulness of MPH administration in Med23 CKO mice, Med23 CKO mice may serve as a novel animal model for studying ADHD-like behaviors and its deficiency-related brain diseases." (PMID 40114018, 2025).
infection (1 paper, 2024). The state of being infected such as from the introduction of a foreign agent such as serum, vaccine, antigenic substance or organism. "Compared with KrasG12D/+;Med23+/+mice, which had a median survival time of 187 days post-Adeno Cre infection, KrasG12D/+;Med23f/f mice survived a markedly shortener time of only 133 days." (PMID 38195889, 2024). "By 25 weeks post-Adeno Cre infection, no lesions or inflammation were observed in the Med23f/f mice, suggesting that Med23 deletion alone seems not to form lung tumorigenesis by 25 weeks post-Adeno Cre infection." (PMID 38195889, 2024).
skeletal dysplasia (1 paper, 2016). Any Mendelian diseases that affects growth and development of the skeleton. "Our study demonstrated that the Mediator subunit MED23 acts as a cofactor of RUNX2 in the regulation of osteoblast differentiation and bone development, providing an insight into the regulation of RUNX2 activity and skeletal dysplasias such as CCD." (PMID 27033977, 2016).
MED23 also shares sentences with these, for which no sentence is quoted: Alzheimer disease (1 paper); atrial fibrillation (1); Cerebellar atrophy (1); Choreoathetosis (1); colorectal cancer (1); diabetic cardiomyopathy (1); dilated cardiomyopathy (1); Dystonia (1); heart failure (1); hyperthyroidism (1); ischemia (1); latent infections (1); metabolic disorders (1); neurodevelopmental disorder (1); non-small cell lung carcinoma (1); papillary carcinoma (1).